E2F6 (E2F transcription factor 6)
Description:
Inhibitor of E2F-dependent transcription. Binds DNA cooperatively with DP proteins through the E2 recognition site, 5'-TTTC[CG]CGC-3'. Has a preference for the 5'-TTTCCCGC-3' E2F recognition site. E2F6 lacks the transcriptional activation and pocket protein binding domains. Appears to regulate a subset of E2F-dependent genes whose products are required for entry into the cell cycle but not for normal cell cycle progression. Represses expression of some meiosis-specific genes, including SLC25A31/ANT4 (By similarity). May silence expression via the recruitment of a chromatin remodeling complex containing histone H3-K9 methyltransferase activity. Overexpression delays the exit of cells from the S-phase.
Synonyms: E2F-6
Tractability: PROTAC: UniProt records ubiquitination sites on it; ubiquitination databases record sites on it. Other modalities: a drug acting on it is in phase 2 or 3 trials.
Gene: Protein-coding gene on chromosome 2 (11,444,375 to 11,466,177, reverse strand). Ensembl gene ENSG00000169016.
Subcellular location: Nucleus
Subcellular location (Human Protein Atlas): Nucleoplasm
Pathways (Reactome):
Cell Cycle: G1/S-Specific Transcription
Gene expression (Transcription): Transcriptional Regulation by E2F6
Gene Ontology:
Molecular function: DNA-binding transcription repressor activity, RNA polymerase II-specific; protein binding; RNA polymerase II transcription regulatory region sequence-specific DNA binding; DNA-binding transcription factor activity, RNA polymerase II-specific; RNA polymerase II cis-regulatory region sequence-specific DNA binding; DNA binding; DNA-binding transcription factor activity; protein dimerization activity; sequence-specific DNA binding
Biological process: negative regulation of transcription by RNA polymerase II; heterochromatin formation; negative regulation of DNA-templated transcription; regulation of transcription by RNA polymerase II; regulation of DNA-templated transcription
Cellular component: MLL1 complex; nucleoplasm; nucleus; RNA polymerase II transcription regulator complex; RNA polymerase II transcription repressor complex; chromatin; PRC1 complex; transcription regulator complex
Genetic constraint (gnomAD): Loss-of-function variants: 15 observed, 21.52 expected, observed/expected ratio (o/e) 0.7, 90% interval 0.47 to 1.07. The upper end of that interval is the gene's LOEUF score, 1.07, which puts it in group 4 of 6, group 1 being the genes least tolerant of losing a copy. Missense variants: 217 observed, 273.37 expected, observed/expected ratio (o/e) 0.79, 90% interval 0.71 to 0.89. Synonymous variants: 100 observed, 102.85 expected, observed/expected ratio (o/e) 0.97, 90% interval 0.83 to 1.15.
Homologues: Orthologues: chimpanzee E2F6 (100% identical), macaque E2F6 (99% identical), dog E2F6 (95% identical), pig E2F6 (94% identical), rat E2f6 (85% identical), mouse E2f6 (84% identical), rabbit E2F6 (84% identical), guinea pig E2F6 (81% identical), tropical clawed frog e2f6 (53% identical), zebrafish e2f6 (29% identical), Caenorhabditis elegans efl-3 (21% identical). Paralogues in human: E2F3 (40% identical), E2F2 (40% identical), E2F1 (34% identical), E2F4 (28% identical), E2F5 (27% identical), E2F7 (22% identical), E2F8 (21% identical).
Diseases named in the same sentence as E2F6 in open-access papers:
E2F6 is named in the same sentence as 65 diseases in open-access papers, as found by Europe PMC text mining. Sharing a sentence is not in itself a finding about the gene and the disease. The quoted sentences say what the papers report.
ovarian carcinoma (15 papers, 2014 to 2024). A malignant neoplasm originating from the surface ovarian epithelium. "Taken together, these results highlight the role of miR-454 as a tumor suppressor in ovarian cancer cells by targeting E2F6, indicating that miR-454 may be a potential diagnostic biomarker and therapeutic target for ovarian cancer." (PMID 32536825, 2020). "E2F transcription factor 6 (E2F6) is upregulated in ovarian cancer when estrogen (E2) binds to the estrogen receptor (ER)." (PMID 39170516, 2024). "Consistent with this mathematical model, a recent study also demonstrated that inhibition of E2F6 suppressed tumor growth and migration in ovarian cancer." (PMID 35216394, 2022). "It was demonstrated lncRNA TMPO-AS1 potentially fosters LCN2 transcriptional activity by binding to TF E2F6, and thus, stimulates the progression of ovarian cancer." (PMID 34858481, 2021). "Upregulation of E2F6 mRNA expression, in turn, was found to upregulate the stemness marker c-Kit through E2F6-mediated silencing of miR‐193a and to promote ovarian cancer stemness and tumorigenesis." (PMID 34476219, 2021). "For instance, lncRNA TMPO-AS1 boosts the transcription activity of LCN2 by binding to the TF E2F6, thereby facilitating the development of ovarian cancer." (PMID 34858481, 2021). "For example, lncRNA TMPO-AS1 hastens the transcriptional activity of LCN2 by binding to the TF E2F6, thereby boosting the development of ovarian cancer." (PMID 34858481, 2021). "We have previously demonstrated that E2F6-mediated EZH2 repression is responsible for the epigenetic silencing of miR-193a in ovarian cancer." (PMID 33718136, 2021). "For example, miR-454 restrained the growth and invasion of ovarian cancer cells via regulating E2F6." (PMID 33968126, 2021). "E2F6 belongs to the family of E2F transcription factors, and has been reported to exert oncogenic functions in several gynecological cancers, such as ovarian cancer and endometrial carcinoma, but the role of E2F6 in CC remains elusive." (PMID 31682716, 2020). "The expression pattern of E2F6 in ovarian cancer tissues was detected using immunohistochemistry (IHC) assay." (PMID 32536825, 2020). "Mechanically, bioinformatic analysis and dual-luciferase reporter assay confirmed that E2F6 was a direct target of miR-454 and negatively regulated by miR-454 in ovarian cancer cells." (PMID 32536825, 2020). "The rate of E2F6-high expression in ovarian cancer tissues was 57.3% (43/75), which was 20% (3/15) in tumor-adjacent tissues (P < 0.05)." (PMID 32536825, 2020). "Multiple studies have revealed the up-regulation and oncogenic function of E2F6 in cancers, such as ovarian cancer and endometrial carcinoma." (PMID 31682716, 2020). "The IHC analysis was performed to determine the expression of E2F6 protein in 75 cases of ovarian cancer tissues and 15 cases of tumor-adjacent tissues." (PMID 32536825, 2020). "Mechanically, E2F6 was identified as a direct target of miR-454, which was up-regulated in ovarian cancer tissues and involved in the tumor suppressive role of miR-454." (PMID 32536825, 2020). "In particular, we recently demonstrated that estrogen receptor-driven upregulation of E2F6 can ‘sponge’ miR-193a, to facilitate c-Kit overexpression, in ovarian cancer." (PMID 31569404, 2019). "Recently, a mathematical model on how E2F6 functions to promote ovarian cancer stemness has been described." (PMID 31768102, 2019). "To investigate the relationship between miR-193a and c-KIT/E2F6 in ovarian cancer, we over-expressed miR-193a in A2780 ovarian cancer cells which have low levels of miR-193a expression." (PMID 25545504, 2014). "Such phenomenon can be observed in normal ovarian epithelial cells or ovarian cancer cells in which the E2F6 inhibition efficiency is low." (PMID 25545504, 2014). "Moreover, TMPO-AS1 has the potential to enhance LCN2 transcriptional activity by binding to transcription factor E2F6, thus stimulating ovarian cancer progression." (PMID 37592311, 2023).
ovarian carcinoma (continued). "Thus, the reversible/irreversible feature of c-KIT mRNA regulation processes by different E2F6 inhibition strength can partially explain the clinical observation that anti-estrogen therapy is only partially effective in the treatment of ovarian cancer." (PMID 35216394, 2022). "It has been further verified that the estrogen-mediated E2F6-miR-193a-EZH2 network could promote stemness of ovarian cancer cells via in vitro and in vivo experiments." (PMID 34122542, 2021). "In addition, we demonstrated that E2F6 was significantly up-regulated in ovarian cancer tissues, and E2F6 overexpression significantly enhanced the proliferation and invasion abilities of ovarian cancer cells." (PMID 32536825, 2020). "Therefore, our findings suggest that miR-454 impedes the growth and metastasis of ovarian cancer by targeting E2F6." (PMID 32536825, 2020). "In the present study, by bioinformatics analysis and dual-luciferase reporter assay, we verified that E2F6 was a direct target of miR-454 in ovarian cancer cells, and miR-454 could negatively regulate the expression of E2F6." (PMID 32536825, 2020). "Additionally, we observed that E2F6 protein was highly expressed in ovarian cancer tissues compared with tumor-adjacent tissues." (PMID 32536825, 2020). "Collectively, E2F6 acts as a functional target of miR-454 in ovarian cancer." (PMID 32536825, 2020). "It has been shown that treatment of immortalized ovarian surface epithelial cells with estrogen upregulated E2F6,which, in turn, competitively inhibited the activity of microRNA-193a (which usually prevents cancer stemness), thereby stimulating ovarian cancer stemness and tumorigenesis." (PMID 31768102, 2019). "Interestingly, ovarian cancer patients with low EZH2 level show a positive correlation between the expression of E2F6 and c-KIT." (PMID 25545504, 2014). "Indeed, components of transcriptional repressors such as EZH2 which is required for transcriptional suppression of E2F6 is found to be low in normal ovarian cells and a sub-set of ovarian cancer." (PMID 25545504, 2014). "Similarly, the transcription factor E2F6 can also function as a ceRNA, inhibiting the effects mediated by the tumor suppressor miR-193a and promoting the stemness of ovarian cancer cells (HeyC2) through the upregulation of the ovarian cancer stemness marker c-KIT." (PMID 34439740, 2021). "Therefore, E2F6 was a direct target of miR-454 in ovarian cancer cells." (PMID 32536825, 2020). "Moreover, IHC analysis showed that E2F6 was highly expressed in ovarian cancer tissues." (PMID 32536825, 2020). "As the role of miR-193a in ovarian cancer is currently unknown, we hypothesize that E2F6 protein may suppress the expression of miR-193a, both directly as a DNA-binding transcriptional repressor and indirectly through promotion of the polycomb complex assembly." (PMID 25545504, 2014). "Expression of miR-193a resulted in a significant down-regulation of c-KIT mRNA and E2F6 mRNA, thus suggesting that c-KIT mRNA and E2F6 mRNA are targets of miR-193a in ovarian cancer cells." (PMID 25545504, 2014). "Additional analysis of the TCGA ovarian cancer dataset demonstrates that ovarian cancer patients with low expression of EZH2, a polycomb-group family protein, show positive correlation between E2F6 and c-KIT." (PMID 25545504, 2014). "Importantly, a positive correlation of E2F6 and c-KIT is only observed in ovarian cancer patients with low EZH2 expression." (PMID 25545504, 2014). "Importantly, this is also consistent with the clinical evidence that the expression of E2F6 and c-KIT are correlated in ovarian cancer patients with low expression of EZH2 but not in cases of high EZH2 expression." (PMID 25545504, 2014).
breast cancer (11 papers, 2012 to 2025). A primary or metastatic malignant neoplasm involving the breast. "A previous study also revealed that E2F6 repressed the oncogenic lncRNA H19 expression in breast cancer cells." (PMID 30614188, 2019). "In the present study, we considered it possible that E2F6 plays a role in responding to endogenous replication stress in breast cancer cells." (PMID 31768102, 2019). "In the four breast cancer cell lines studied, we found that levels of E2F6 protein were higher compared to MCF-10A cells." (PMID 31768102, 2019). "The viability of all three breast cancer cell lines was reduced by E2F6 depletion, while the MCF-10A control cells remained viable." (PMID 31768102, 2019). "Depletion of E2F6 in the breast cancer cells reduced cell viability in MCF-7, T-47D, and MDA-MB-231 cells." (PMID 31768102, 2019). "Here, we show that expression of E2F6 in breast tumor tissues and breast cancer cell lines is higher than in normal cells, supporting the view that E2F6 can be overexpressed in breast carcinomas." (PMID 31768102, 2019). "Examining protein levels from breast cancer cell lines, we found high levels of E2F6 protein, as predicted from the cDNA levels found in tumors." (PMID 31768102, 2019). "We first checked E2F6 expression in tumor cDNAs and the protein level in a range of breast cancer cell lines." (PMID 31768102, 2019). "Numerous studies have reported that E2F6 expression was significant for prognosis in malignancies such as pancreatic cancer, breast cancer and nasopharyngeal carcinoma." (PMID 30487158, 2018). "Recently, studies have reported that E2F6 is oncogenic and that its expression is upregulated in prostate and breast cancer." (PMID 29371986, 2017). "miR-185 suppresses tumor proliferation in breast cancer by directly targeting E2F6 and DNMT1 and indirectly up-regulating BRCA139." (PMID 27686215, 2016). "The overexpression of E2F6 was confirmed in breast tumor cDNA samples and breast cancer cell lines." (PMID 31768102, 2019). "Thus, these cell lines can be used as a good model for the study of E2F6 dependence in breast cancer." (PMID 31768102, 2019). "Then we considered that E2F6 might have a role in responding to endogenous replication stress in breast cancer cells." (PMID 31768102, 2019). "Therefore, this study set out to analyze the expression of E2F6 in breast tumor and breast cancer cell lines and further test its correlation with ER level." (PMID 31768102, 2019). "Whether this high expression of E2F6 is important to the viability of breast cancer cells was further tested in the present study using three specific si-RNAs targeting E2F6 at various regions." (PMID 31768102, 2019). "Here we confirm the overexpression of E2F6 in breast cancers and also test the idea that E2F6 overexpression could be important specifically to the survival of breast cancer cell lines." (PMID 31768102, 2019). "In agreement with this, E2F6 possibly targets different gene promoters in each of the studied normal and cancer cell lines; this needs to be extensively investigated using chromatin immunoprecipitation for further confirmation of this idea, at least in breast cancer." (PMID 31768102, 2019). "The role of miR-185 has been investigated in various cancers including lung cancer, osteosarcoma and breast cancer by targeting SOX9, HK2, DNMT1 and E2F6, respectively." (PMID 33507687, 2021). "Conversely, overexpression of either E2F4 or E2F6, as well as E2F5 which also forms a DREAM complex, was able to repress A3B expression to varying extents in multiple different breast cancer cell lines." (PMID 32985974, 2020).
breast cancer (continued). "qRT-PCR analysis demonstrated that E2F6 mRNA is more highly expressed in breast cancer cell lines than in a nontumor breast epithelial cell line." (PMID 31768102, 2019). "In order to establish a system to investigate the importance of E2F6 overexpression, we determined whether or not the high expression of E2F6 mRNA from the tumor array was also seen in breast cancer cell lines." (PMID 31768102, 2019). "E2F6 has been reported as overexpressed in breast cancers but whether or not this is important for tumor development is unclear." (PMID 31768102, 2019). "To determine whether or not the high expression levels of E2F6 in breast cancer cell lines were important for their survival, we set out to reduce protein levels and looked for any impact on viability." (PMID 31768102, 2019).
glioma (9 papers, 2014 to 2025). A benign or malignant brain and spinal cord tumor that arises from glial cells (astrocytes, oligodendrocytes, ependymal cells). "It is imperative to investigate the role and underlying mechanism of E2F6 in glioma." (PMID 34381702, 2021). "Furthermore, the immumohistochemical (IHC) staining of 31 WHO II patients, 32 WHO III patients, and 54 WHO IV patients proved that elevated levels of E2F6 expression are associated with high grade of glioma." (PMID 31508283, 2019). "qRT-PCR showed that the expression of E2F6 in glioma tissues was higher than that in normal brain tissues and was correlated with the recurrence of glioma." (PMID 34381702, 2021). "Then, with the help of bioinformatics tools and related assays, we demonstrated that COX10-AS1 promoted glioma progression by sponging miR-641 to regulate E2F6." (PMID 34381702, 2021). "Then, with the help of bioinformatics analysis, we confirmed that COX10-AS1 regulated glioma progress by acting as a sponge of miR-641 to regulate E2F6." (PMID 34381702, 2021). "From these candidate genes, we found that E2F6 was upregulated in glioma tissues and cell lines, which was closely related to COX10-AS1 and miR-641." (PMID 34381702, 2021). "Clone formation assays, EdU assays, Transwell assays and tumour xenograft experiments were performed to evaluate the effects of COX10-AS1, miR-641 and E2F6 on glioma proliferation, migration and invasion." (PMID 34381702, 2021). "Taken together, in present study, we showed that E2F6-induced COX10-AS1 promotes glioma progression by acting as a sponge for miR-641 to regulate E2F6." (PMID 34381702, 2021). "Overall, we concluded that COX10-AS1/miR-641/E2F6 formed a positive feedback loop to regulate glioma progression." (PMID 34381702, 2021). "E2F6 expression was significantly higher in neurosphere glioma cells than in differentiated glioma cells." (PMID 31508283, 2019). "To gain insight into the expression profile of E2F6 in glioma samples, we employed The Cancer Genome Atlas (TCGA) RNA‐seq data and microarray data of Rembrandt." (PMID 31508283, 2019). "Moreover, Ki-67 and TUNEL staining suggested that E2F6 was involved in the progression of glioma growth." (PMID 34381702, 2021). "The results demonstrated that E2F6 was higher in glioma cells than in NHAs." (PMID 34381702, 2021). "Clone formation assays and EdU assays demonstrated that sh-E2F6 could inhibit the proliferation of glioma cells and that the inhibitory effect could be rescued by miR-641 inhibitor." (PMID 34381702, 2021). "Taken together, the data indicated that COX10-AS1 acts as an oncogene in combination with COX10-AS1/miR-641/E2F6 in glioma, which may be beneficial to the diagnosis and treatment of glioma." (PMID 34381702, 2021). "Transwell assays showed a similar result whereby sh-E2F6 could inhibit the migration and invasion of glioma cells, and the inhibitory effect could be partly reversed by miR-641 inhibitor." (PMID 34381702, 2021). "We explored E2F6 expression in NHAs and glioma cell lines by qRT-PCR and western blot as well." (PMID 34381702, 2021). "By using rescue assays, we concluded that COX10-AS1/miR-641/E2F6 formed a positive feedback loop in glioma progression, which may provide a theoretical basis for the development of new treatment strategies for glioma." (PMID 34381702, 2021). "We searched for transcription factors that are positively co-expressed with EIF4EBP1 in gliomas and found EIF4EBP1 mRNA expression to be significantly and positively associated with the mRNA expression levels of MYBL2, FOXM1, ETS1, HIF-1A, JUN, E2F1, and E2F6 in the REMBRANDT dataset." (PMID 35228525, 2022). "In addition, we explored the effect of E2F6 on glioma growth in vivo." (PMID 34381702, 2021). "Thus, we assessed if E2F6 was highly expressed in neurosphere glioma cells." (PMID 31508283, 2019).